ALYREF (Aly/REF export factor)
Description:
Functions as an mRNA export adapter; component of the transcription/export (TREX) complex which is thought to couple mRNA transcription, processing and nuclear export, and specifically associates with spliced mRNA and not with unspliced pre-mRNA. TREX is recruited to spliced mRNAs by a transcription-independent mechanism, binds to mRNA upstream of the exon-junction complex (EJC) and is recruited in a splicing- and cap-dependent manner to a region near the 5' end of the mRNA where it functions in mRNA export to the cytoplasm via the TAP/NXF1 pathway. Involved in the nuclear export of intronless mRNA; proposed to be recruited to intronless mRNA by ATP-bound DDX39B. Plays a key role in mRNP recognition and mRNA packaging by bridging the mRNP-bound EJC and the TREX core complex. TREX recruitment occurs via an interaction between ALYREF/THOC4 and the cap-binding protein NCBP1. Required for TREX complex assembly and for linking DDX39B to the cap-binding complex (CBC). Binds mRNA which is thought to be transferred to the NXF1-NXT1 heterodimer for export (TAP/NXF1 pathway). In conjunction with THOC5 functions in NXF1-NXT1 mediated nuclear export of HSP70 mRNA; both proteins enhance the RNA binding activity of NXF1 and are required for NXF1 localization to the nuclear rim. Involved in mRNA export of C5-methylcytosine (m5C)- containing mRNAs: specifically recognizes and binds m5C mRNAs and mediates their nucleo-cytoplasmic shuttling. Acts as a chaperone and promotes the dimerization of transcription factors containing basic leucine zipper (bZIP) domains and thereby promotes transcriptional activation. Involved in transcription elongation and genome stability. (Microbial infection) The TREX complex is essential for the export of Kaposi's sarcoma-associated herpesvirus (KSHV) intronless mRNAs and infectious virus production; ALYREF/THOC4 mediates the recruitment of the TREX complex to the intronless viral mRNA.
Synonyms: ALY; BEF; THOC4; ALY/REF; REF
Gene: Protein-coding gene on chromosome 17 (81,887,835 to 81,891,586, reverse strand). Ensembl gene ENSG00000183684.
Subcellular location: Nucleus; Nucleus speckle; Cytoplasm
Subcellular location (Human Protein Atlas): Nuclear speckles; Nucleoplasm
Pathways (Reactome):
Metabolism of RNA: Transport of Mature mRNA Derived from an Intronless Transcript; Transport of Mature mRNA derived from an Intron-Containing Transcript; Transport of the SLBP Dependant Mature mRNA; Transport of the SLBP independent Mature mRNA; mRNA 3'-end processing; mRNA Splicing - Major Pathway
Disease: Dengue Virus-Host Interactions
Genetic constraint (gnomAD): Loss-of-function variants: 1 observed, 20.18 expected, observed/expected ratio (o/e) 0.0496, 90% interval 0.017 to 0.23. The synonymous counts are far from expectation, so gnomAD's model fits this gene poorly and the ratio says little. Missense variants: 328 observed, 319.44 expected, observed/expected ratio (o/e) 1.03, 90% interval 0.94 to 1.12. Synonymous variants: 193 observed, 136.58 expected, observed/expected ratio (o/e) 1.41, 90% interval 1.26 to 1.59.
Homologues: Orthologues: chimpanzee ALYREF (98% identical), macaque ALYREF (98% identical), dog ALYREF (97% identical), guinea pig ALYREF (94% identical), mouse Alyref (94% identical), rat Alyref (94% identical), tropical clawed frog alyref (78% identical), mouse Alyref2 (75% identical), pig ALYREF (73% identical), mouse Alyreffm10 (66% identical), mouse Alyreffm11 (66% identical), mouse Alyreffm13 (66% identical), and 16 more. Paralogues in human: POLDIP3 (28% identical), CHTOP (25% identical).
Diseases named in the same sentence as ALYREF in open-access papers:
ALYREF is named in the same sentence as 70 diseases in open-access papers, as found by Europe PMC text mining. Sharing a sentence is not in itself a finding about the gene and the disease. The quoted sentences say what the papers report.
breast carcinoma (19 papers, 2011 to 2025). "Recent research has linked ALYREF to the development of various tumors, including bladder cancer, breast cancer, neuroblastoma, hepatocellular carcinoma, glioblastoma, and non-small cell lung cancer." (PMID 38361753, 2024). "ROC curve analysis was conducted to determine the diagnostic values of DNMT3B and ALYREF in breast cancer." (PMID 35812757, 2022). "Overall, we found that the ALYREF gene is amplified in human cancers and that high expression levels are associated with poor clinical outcome in human breast cancer." (PMID 35776213, 2022). "Using a breast cancer screening cohort (n = 128), we identified high levels of intra-tumoral ALYREF mRNA expression as significantly associated with poor disease-free survival (p = 0.041, log-rank test) and poor overall survival (p = 0.009, log-rank test)." (PMID 35776213, 2022). "Next, ROC curve analysis for DNMT3B and ALYREF revealed their significant diagnostic roles in breast cancer." (PMID 35812757, 2022). "As breast cancer is a heterogenous disease in terms of underlying biology, we analyzed different subtypes (by using the online tool bc-GenExMiner v4.7) and identified the highest ALYREF mRNA expression in the basal-like subtype and TNBC." (PMID 35776213, 2022). "A previously published study showed higher ALYREF protein expression in tumor tissue compared to normal breast tissue and using a publicly available cohort of breast cancer patients (n = 65), high ALYREF protein expression was associated with worse patient survival." (PMID 35776213, 2022). "Given the findings that the ALYREF gene region is amplified in breast cancer and ALYREF mRNA is upregulated in cancerous tissue, we further explored the relevance of intra-tumoral ALYREF mRNA expression level and its association with clinical outcome in patients." (PMID 35776213, 2022). "High expression level of ALYREF has been shown to be a significant factor in poor survival in breast cancer patients, and facilitated the tumorigenesis of breast cancer cells in mice." (PMID 38491127, 2024). "In breast cancer cells, the abundance of lncRNA modified by ALYREF is high, which promotes the development of tumours by affecting the apoptosis and mitochondrial energy metabolism of cancer cells." (PMID 39187946, 2024). "To clarify the human relevance of ALYREF expression in breast cancer, we explored chromosomal alterations of the ALYREF gene region in more than 10,000 patients throughout 32 cancer types in the TCGA-PanCancer Atlas dataset." (PMID 35776213, 2022). "Both DNMT3B and ALYREF possessed the significant abilities to distinguish breast cancer tissues from normal breast tissues." (PMID 35812757, 2022). "For ALYREF, its expression in triple-negative breast cancer was highest and in luminal breast cancer was lowest." (PMID 35812757, 2022). "Among 13 m5C regulators, DNMT3B and ALYREF were significantly upregulated in breast cancer and their high expression indicated unfavorable prognosis." (PMID 35812757, 2022). "The explore ALYREF protein expression patterns in breast cancer, we found that the protein is strongly expressed in tumor samples of breast cancer patients, with the highest protein expression found in the basal subtype." (PMID 35776213, 2022). "ALYREF was significantly upregulated in several tumour tissues, including breast cancer." (PMID 39915011, 2025). "Breast cancer displays high ALYREF expression that correlates to poor survival." (PMID 36969033, 2023). "Knockout of ALYREF changes multiple phenotypes of liver cancer and breast cancer." (PMID 37934565, 2023). "All these findings together indicate that DNMT3B and ALYREF may be two most potential oncogenes in breast cancer among all these m5C regulators." (PMID 35812757, 2022). "Importantly, there are no data so far published reporting the clinical relevance of ALYREF in breast cancer or TNBC." (PMID 35776213, 2022).
breast carcinoma (continued). "DNMT3B and ALYREF might be the most potential functional m5C regulators and promising biomarkers in breast cancer." (PMID 35812757, 2022). "Moreover, DNMT3B and ALYREF protein levels in breast cancer tissues were also obviously higher than that in normal breast tissues." (PMID 35812757, 2022). "Our survival analyses of two independent breast cancer cohorts showed consistent results and suggest ALYREF as a novel prognostic biomarker that might be useful in the stratification of patients according to their individual risk." (PMID 35776213, 2022). "Moreover, we found that, among these m5C regulators, ALYREF was most highly expressed in breast cancer." (PMID 35812757, 2022). "Here, we identified high ALYREF expression as a factor for poor survival in breast cancer patients." (PMID 35776213, 2022). "However, the significantly higher expression especially in basal-like breast cancer might open a therapeutic window to use ALYREF as a therapeutic molecule." (PMID 35776213, 2022). "Comparison of the expression patterns of the m5C machinery across breast cancer subtypes revealed that the m5C methyltransferase NSUN5 and the readers ALYREF, YBX1, and YBX2 were overexpressed in the basal subtype relative to normal tissue." (PMID 40918643, 2025). "Intriguingly, only breast cancer patients with higher expression of DNMT3B and ALYREF had poorer OS and RFS." (PMID 35812757, 2022). "Research on bladder cancer, breast cancer, HCC, and oral squamous cell carcinoma revealed that ALYREF and YBX1 were upregulated as well." (PMID 36389669, 2022). "Expression of NSUN1, NSUN2, NSUN5, DNMT1, DNMT3A, DNMT3B, and ALYREF was significantly increased, but DNMT2 and TET2 expression was markedly decreased in breast cancer tissues when compared with normal breast tissues." (PMID 35812757, 2022). "High expression of ALYREF was found to selectively regulate the short isoform of nuclear paraspeckle assembly transcript 1 (NEAT1) to impact energy metabolism and promote tumour growth in breast cancer." (PMID 39915011, 2025). "High expression of ALYREF correlates with poor prognosis in patients, as evidenced in hepatocellular carcinoma (HCC), glioblastoma, glioma, neuroblastoma, lung adenocarcinoma, bladder cancer, and breast cancer." (PMID 39062595, 2024). "As there are no systematic studies of ALYREF and its role in human breast cancer, we aimed for the first time to explore and comprehensively characterize the putative role of this RNA-binding protein and transcriptional activator in human breast carcinogenesis." (PMID 35776213, 2022). "Our study is not answering whether targeting ALYREF in normal cells or normal breast epithelial, will result in the same effects when targeting breast cancer cells." (PMID 35776213, 2022). "Further analysis revealed that more than half of DNMT3B/ALYREF-miRNA pairs showed positive expression correlation (51.3% for DNMT3B and 55.0% for ALYREF) in breast cancer, but only 10.1 and 25.0% pairs presented negative expression relationship for DNMT3B and ALYREF, respectively." (PMID 35812757, 2022).
bladder cancer (16 papers, 2020 to 2026). "ALYREF is highly expressed in bladder cancer and is associated with a poor prognosis." (PMID 40809690, 2025). "PKM2 and ALYREF levels have been associated to poor outcomes in bladder cancer patients, suggesting that ALYREF and its target gene PKM2 might be helpful biomarkers for guiding early bladder cancer diagnosis." (PMID 38436027, 2024). "Bladder cancer research has shown that NSUN2 co-exists with Aly/REF export factor (ALYREF), contributing to bladder cancer proliferation, invasion, and poor prognosis." (PMID 40809690, 2025). "It is worth noting that ALYREF expression also showed significant positive correlation with monocyte/macrophage infiltration in bladder cancer, suggesting a potential role of m5C regulators in shaping tumor immune microenvironments." (PMID 40405297, 2025). "Previous studies have reported that overexpression of ALYREF promotes bladder cancer cell proliferation via PKM2-mediated glycolysis." (PMID 38579085, 2024). "Additionally, studies on bladder cancer showed that the Aly/REF export factor (ALYREF) stabilized PKM2 expression by binding to the 3′‐untranslated region 5‐methylcytidine site in the messenger RNA (mRNA) of PKM2." (PMID 39584783, 2024). "ALYREF may act as a poor prognosis biomarker in patients with bladder cancer and is involved in glycolysis and cell proliferation by regulating PKM2." (PMID 36246622, 2022). "Specifically, m5C-mediated ALYREF recognizes RABL6 and TK1 mRNA m5C modification through its K171 domain, enhancing mRNA splicing and stability to increase bladder cancer malignancy." (PMID 40809690, 2025). "Through its K171 domain, ALYREF recognizes RABL6 and TK1 mRNA m5C modification, promoting their mRNA splicing and stability to increase bladder cancer malignancy." (PMID 40809690, 2025). "An upregulation of another reader, ALYREF, under the HIF1A control, contributes to enhanced glucose metabolism in bladder cancer." (PMID 39164641, 2024). "Notably, ALYREF was activated by HIF‐1α, thereby promoting glycolysis and the development of bladder cancer, suggesting its role in hypoxia during tumorigenesis." (PMID 40914946, 2026). "Moreover, two m5C reader proteins are known: the Aly/ REF export factor (ALYREF) regulating the nuclear export of modified mRNAs and the recently discovered Y-box binding protein 1 (YBX1) promoting bladder cancer by enhancing stability of target mRNAs." (PMID 32630140, 2020).
hepatocellular carcinoma (15 papers, 2021 to 2025). A malignant tumor that arises from hepatocytes. "Aly/REF export factor (ALYREF) is upregulated in hepatocellular carcinoma and is associated with poor prognosis." (PMID 40448344, 2025). "The m5C reader ALYREF expression was dysregulated in several cancers, and higher ALYREF expression was associated with poor prognosis in hepatocellular carcinoma." (PMID 35603206, 2022). "Overexpression of ALYREF was found to promote cancer progression by mediating RNA m5C modification in hepatocellular carcinoma." (PMID 39915011, 2025). "Chen Xue reported that ALYREF mediates RNA m5C modification to promote hepatocellular carcinoma progression." (PMID 38238581, 2024). "In addition, pancancer progression-free interval (PFI) analysis in TCGA revealed that ALYREF is an unfavorable factor in kidney chromophobe, uveal melanoma, glioma, and hepatocellular carcinoma." (PMID 37155024, 2023). "Next, ALYREF was found to be upregulated in hepatocellular carcinoma and oral squamous cell carcinoma, and it may have an effect on tumorigenesis via cell cycle regulation and mitosis." (PMID 35281843, 2022). "However, the specific expression levels and functional roles of ALYREF in cancers are largely unknown, including for hepatocellular carcinoma (HCC)." (PMID 34367948, 2021). "In sorafenib-resistant hepatocellular carcinoma (HCC), NSUN2 cooperates with ALYREF to maintain the stability and high expression of the long non-coding RNA MALAT1 via its m5C methyltransferase activity." (PMID 41256859, 2025).
glioma (8 papers, 2021 to 2025). A benign or malignant brain and spinal cord tumor that arises from glial cells (astrocytes, oligodendrocytes, ependymal cells). "In glioma, NSUN2-mediated m5C modification in the 3’-UTR of ATX mRNA strengthens its interaction with the reader protein ALYREF, facilitating nuclear export of the transcript and promoting glioma cell migration." (PMID 41446042, 2025). "Recently, it has been found that ALYREF was upregulated in gliomas, suggesting its potential as a prognostic predictor of GBM." (PMID 37964279, 2023). "Applying univariant and multivariant CoxPH analysis, we proved that ALYREF, DNMT3B, NSUN4 and NSUN6 were independent prognostic factors for glioma." (PMID 37934565, 2023). "In glioma cells, NSUN2 facilitates m5C methylation to promote the export of ATX mRNA from the nucleus to the cytoplasm in an ALYREF-dependent manner, thereby regulating ATX mRNA expression via methylation and affecting cell migration." (PMID 37964279, 2023).
glioblastoma (7 papers, 2017 to 2024). The most malignant astrocytic tumor (WHO grade IV). "In patients with glioblastoma, the most aggressive diffuse glioma, upregulated ALYREF plays an oncogenic role by activating the Wnt/β-catenin signaling pathway and stabilizing MYC mRNA." (PMID 37325635, 2023). "The overexpression of ALYREF is known to occur in glioblastoma, and its function is considered a putative target for glioblastoma therapy to regulate mRNA splicing." (PMID 34367948, 2021). "ALYREF is reported to be an important oncogenic factor and is associated with poor prognosis in patients with various types of cancer, including HCC, glioblastoma, glioma, neuroblastoma, lung adenocarcinoma, HNSCC, bladder cancer and breast cancer." (PMID 37325635, 2023). "We also observed changes in expression of four RNA processing regulators previously identified in genomic/functional screening for RNA binding proteins contributing to glioblastoma phenotypes: MAGOH, PPIH, ALYREF, and SNRPE70." (PMID 32488114, 2020).
non-small cell lung carcinoma (7 papers, 2023 to 2025). A group of at least three distinct histological types of lung cancer, including non-small cell squamous cell carcinoma, adenocarcinoma, and large cell carcinoma. "Meanwhile, ALYREF was suggested to function as an oncogenic factor in non-small cell lung cancer (NSCLC) by stabilizing LINC0215932." (PMID 38491127, 2024). "LINC02159 promotes non-small cell lung cancer progression via ALYREF/YAP1 signaling." (PMID 40091620, 2025). "In non-small cell lung cancer (NSCLC), both NSUN2 and its m5C reader protein ALYREF are significantly upregulated and contribute to tumor cell proliferation and progression." (PMID 41256859, 2025).